CD47 (CD47 molecule)
Diseases named in the same sentence as CD47 in open-access papers (continued):
Sharing a sentence is not in itself a finding about the gene and the disease.
osteosarcoma (continued). "To address this deficiency, we sought to evaluate the therapeutic effects of CD47 blockade using specific antibodies against osteosarcoma progression." (PMID 26093091, 2015). "Furthermore, we examined the effect of CD47 on the cell viability, apoptosis, migration, and phagocytosis of osteosarcoma cells, exploring its potential as a candidate for osteosarcoma immunotherapy." (PMID 39594611, 2024). "Furthermore, prospective studies should focus on fortifying phagocytic activity and aligning it with effector T-cell functions, with the ultimate goal of establishing a more nuanced understanding of the potential role of CD47 in osteosarcoma immunotherapy." (PMID 39594611, 2024). "In a wound-healing assay, CD47 inhibited the migration of osteosarcoma cells." (PMID 39594611, 2024). "We evaluated the potential of CD47 as an immunotherapy target in osteosarcoma cells." (PMID 39594611, 2024). "And our in vitro study suggested that CD47 can suppress the migration of osteosarcoma cells." (PMID 39594611, 2024). "Our results demonstrated that the CD47 antibody and silencing with siRNA could suppress the migration of osteosarcoma cells, which may be used in treating metastatic osteosarcoma." (PMID 39594611, 2024). "This study evaluated the feasibility of using CD47 as a potential therapeutic target for osteosarcoma and investigated the correlation between CD47 expression and clinicopathological characteristics using biopsy samples obtained from patients with osteosarcoma." (PMID 39594611, 2024). "Because a high expression of CD47 on tumour cells might be a new target in treating sarcoma patients, the use of CD47 antibodies has been tested using both in vitro and in vivo models of leiomyosarcoma, as well as a xenograft model of human osteosarcoma." (PMID 36900335, 2023). "In addition, a combination of doxorubicin and CD47 antibody treatment induced comparable anti-cancer effects in osteosarcoma to that induced by combine treatment of doxorubicin with BCH." (PMID 36274066, 2022). "To determine whether chemotherapy alters the expression of CD47, we performed immunohistochemistry (IHC) analysis to assess CD47 protein levels in paired specimens from 81 osteosarcoma patients before and after chemotherapy." (PMID 36274066, 2022). "In addition, the expression of IL-18 and CD47 in osteosarcoma specimens before and after chemotherapy was correlated, and the changes of CD47 expression caused by chemotherapy were also correlated with the changes of IL-18 induced by chemotherapy." (PMID 36274066, 2022). "Notably, clodronate liposome treatment reduced both basal CD47 expression and doxorubicin-induced CD47 upregulation in osteosarcoma." (PMID 36274066, 2022). "In addition, the expression of LAT2 was positively correlated with expression of IL-18 as well as the expression of CD47 in osteosarcoma specimens before and after chemotherapy." (PMID 36274066, 2022). "In addition, we observed positive correlations between CD47 and IL-18 in three different GEO cohorts of osteosarcoma patients." (PMID 36274066, 2022). "In support of this clinical observation, CD47 blockade appeared to decrease in vivo pulmonary metastatic formation in mouse xenograft models and increase tumor-associated macrophage (TAM) phagocytosis of osteosarcoma cells." (PMID 35582455, 2020). "Although there are limited studies on anti-CD47/SIRPα therapy in osteosarcoma, these suggested strategies targeting CD47/SIRP-α that turn the ‘don’t eat me’ signal off may be an efficient therapy in osteosarcoma." (PMID 33363016, 2020). "CD47 mAb treatment combined with chemotherapy increased the number of macrophages and further enhanced their phagocytic capabilities in osteosarcoma, thus produced a better outcome in the osteosarcoma-bearing mice model." (PMID 33363016, 2020). "We investigated with confocal microscopy whether treatment with CD47 mAb activates the phagocytic activity of macrophages in vitro, in co-cultures with Saos-2 osteosarcoma cells." (PMID 30674867, 2019).
osteosarcoma (continued). "This could represent a significant breakthrough for clinicians as a new gold-standard imaging test for treatment stratification and tracking TAM response in upcoming CD47 mAb immunotherapy trials of osteosarcomas and other solid tumors." (PMID 30674867, 2019). "To investigate whether ferumoxytol-MRI can detect in vivo macrophage response in subcutaneous osteosarcomas, we injected osteosarcoma-bearing mice with ferumoxytol and obtained MR imaging studies before and after CD47 mAb or sham treatment." (PMID 30674867, 2019). "Thus, the purpose of our study was to compare the efficacy of CD47 mAb plus doxorubicin combination therapy in mouse models of osteosarcoma with CD47 mAb and doxorubicin monotherapy." (PMID 31376208, 2019). "Our data showed a strong additive effect of doxorubicin plus CD47 mAb combination therapy in mouse models of osteosarcomas, which led to significantly inhibited tumor growth and significantly improved survival of tumor‐bearing mice compared to CD47 mAb alone and doxorubicin alone." (PMID 31376208, 2019). "Furthermore, co-cultures of F4/80+ macrophages, MNNG/HOS osteosarcoma cells and CD47 mAb lead to significantly increased ferumoxytol nanoparticle phagocytosis by macrophages (p = 0.01) as compared to co-cultures with control antibody." (PMID 30674867, 2019). "To investigate whether ferumoxytol-MRI can detect changes in TAM quantities in orthotopic osteosarcomas, we injected osteosarcoma-bearing mice with ferumoxytol and obtained MR imaging studies before and after CD47 mAb or sham treatment." (PMID 30674867, 2019). "Therefore, the purpose of our study was to evaluate if ferumoxytol-MRI can monitor TAM response to CD47 mAb therapy in osteosarcomas." (PMID 30674867, 2019). "We hypothesize that combined therapy of osteosarcomas with doxorubicin and CD47 mAb will significantly increase the efficacy of either drug alone." (PMID 31376208, 2019). "Thus, we conclude that ferumoxytol-MRI can detect TAM response to CD47 mAb in mouse models of osteosarcoma." (PMID 30674867, 2019). "Our results demonstrated that CD47 blockade in vivo may lead to enhanced phagocytic activity of macrophages against osteosarcoma." (PMID 26093091, 2015). "We next analyzed whether anti-CD47 Abs could inhibit the invasion of osteosarcoma cells through Matrigel-coated filters." (PMID 26093091, 2015). "In conclusion, we have found that CD47 was over expressed on primary osteosarcoma." (PMID 26093091, 2015). "In conclusion, our findings demonstrate that CD47 is a critical regulator in the metastasis of osteosarcoma and suggest that targeted inhibition of this antigen by anti-CD47 may be a novel immunotherapeutic approach in the management of this tumor." (PMID 26093091, 2015). "In addition, blockade of CD47 by specific Abs suppresses the invasive ability of osteosarcoma tumor cells and further inhibits spontaneous pulmonary metastasis of KRIB osteosarcoma cells in vivo." (PMID 26093091, 2015). "We anticipate that CD47 therefore serves as an attractive target for tumor therapy on osteosarcoma." (PMID 26093091, 2015). "Therefore, CD47 protein expression may serve as a valuable prognostic indicator for osteosarcoma, and targeting CD47 is a promising potential therapeutic approach for this malignancy." (PMID 39594611, 2024). "CD47 monoclonal antibody (aCD47) can prevent the binding of CD47 and SIRPα, thereby promoting tumor cell phagocytosis by TAMs and DCs; however, many challenges remain to be overcome in application of aCD47 in osteosarcoma, including low immune response rates and systemic side effects." (PMID 38560565, 2024). "Therefore, combination therapy with Ce6-mediated PDT and CD47 blockage may serve as a novel strategy for osteosarcoma treatment." (PMID 38560565, 2024). "Therefore, CD47 is a potential immunotherapeutic target for osteosarcoma." (PMID 39594611, 2024).
osteosarcoma (continued). "However, whether CD47 expression in osteosarcoma cells is regulated in response to chemotherapy, thereby promoting tumor immune evasion, is unknown." (PMID 36274066, 2022). "Although the prognostic relevance of CD68+ and CD163+ macrophage infiltration in osteosarcoma was not described, lower SIRPα levels were associated with a worse overall survival among non-translocation sarcomas, and CD47 expression turned out to be a poor prognostic factor in osteosarcomas." (PMID 33802565, 2021). "Doxorubicin has been found to induce immunogenic cell death by upregulating signals that encourage TAM-mediated cell clearance, suggesting that a combination of a monoclonal anti-CD47 antibody (CD47 mAb) and doxorubicin could increase drug efficacy in osteosarcoma." (PMID 32961800, 2020). "Furthermore, patients with osteosarcoma tumors that had higher CD47 expression fared poorly." (PMID 26093091, 2015). "We found that CD47 blockade could inhibit tumor growth in the xenograft models of osteosarcoma." (PMID 26093091, 2015). "Finally, CD47 blockade increases macrophage phagocytosis of osteosarcoma tumor cells." (PMID 26093091, 2015). "In addition, CD47 was detected in all primary and xenograft samples from osteosarcoma patients." (PMID 26093091, 2015). "With the exception of B7-H2, all measured immune checkpoint proteins—CD48, TIMD-4, B7-H6, CD134, B7-H5, CD47, and S100A8/A9—were significantly elevated in osteosarcoma patients compared to healthy controls (p < 0.05)." (PMID 40963634, 2025). "An ongoing phase I clinical trial (NCT04751383) is testing the combination therapy of magrolimab (anti-CD47) and dinutuximab (anti-GD2) in patients with relapsed or refractory neuroblastoma or relapsed osteosarcoma." (PMID 38279265, 2024). "In this study, mice with osteosarcoma with pulmonary metastases were treated with a control antibody, anti-GD2, anti-CD47, or a combination of both anti-GD2 and anti-CD47." (PMID 38279265, 2024). "Increased uptake of leucine and glutamine in osteosarcoma cells through upregulation of LAT2 activates mTORC1 and subsequent c-Myc-mediated transcription of CD47, enabling evasion of innate immune mechanisms and thereby promoting metastasis." (PMID 37197432, 2023). "To identify the macrophage-secreted factors responsible for CD47 upregulation, we performed gene set enrichment analysis (GSEA) analyses with GEO data on osteosarcoma patients with high or low CD47 expression level." (PMID 36274066, 2022). "By treating these mice with an anti-CD47 antibody (B6H12), spontaneous metastasis of xenograft osteosarcoma cancer cells to the lung was inhibited, and phagocytosis of the osteosarcoma cells by macrophages enhanced." (PMID 32082311, 2020). "Our team introduced ferumoxytol‐enhanced MRI as a new imaging biomarker for CD47 mAb‐mediated changes in TAM quantities and phagocytic activity in mouse models of MNNG/HOS osteosarcomas." (PMID 31376208, 2019). "Our data showed that ferumoxytol-enhanced MRI can detect CD47 mAb-mediated changes in TAM quantities and phagocytic activity in mouse models of osteosarcomas." (PMID 30674867, 2019). "Intratibial osteosarcomas demonstrated significantly stronger ferumoxytol enhancement and significantly increased TAM quantities after CD47 mAb plus doxorubicin combination therapy compared to CD47 mAb (P = 0.02) and doxorubicin monotherapy (P = 0.001)." (PMID 31376208, 2019). "Moreover, CD47 expression demonstrates an improvement in osteosarcoma metastasis and the utilization of Anti-CD47 Abs eliminates spontaneous metastasis of KRIB osteosarcoma cells via the potentiation of macrophages phagocytosis." (PMID 32902664, 2021). "The use of a monoclonal antibody against CD47 was not, however, able to entirely eradicate osteosarcoma in a mouse model, suggesting that it, like other antibody-based treatments of osteosarcoma, is not sufficient as a monotherapy." (PMID 32961800, 2020).
osteosarcoma (continued). "To evaluate the effect of doxorubicin and CD47 mAb on TAM in osteosarcomas, we can leverage a new imaging technique that can noninvasively monitor the phagocytic activity of TAM in vivo." (PMID 31376208, 2019). "Further western-blot (WB) and immunohistochemistry (IHC) demonstrated that CD47 protein level was highly expressed in osteosarcoma compared to normal osteoblastic cells and adjacent non-tumorous tissues." (PMID 26093091, 2015). "We first found that up-regulation of CD47 mRNA levels in the tumorous tissues from eight patients with osteosarcoma when compared with that in adjacent non-tumorous tissues." (PMID 26093091, 2015). "To get a first insight into the role of CD47 in osteosarcoma, we evaluated CD47 expression in freshly isolated osteosarcoma tissues and adjacent non-tumorous tissues." (PMID 26093091, 2015). "In vitro, CD47 antibody (B6H12) did not affect osteosarcoma cell viability or apoptosis." (PMID 39594611, 2024). "Due to these limitations, we could not explore the correlation between CD47 expression and metastasis in osteosarcoma biopsy samples in depth." (PMID 39594611, 2024). "Consistently, the level of CD47 was elevated in osteosarcoma cells compared to non-tumor cells." (PMID 37056934, 2023). "Within each antibody concentration and duration of exposure, there was no significantly difference of the viability of normal osteoblastic cells and osteosarcoma tumor cells treated with CD47 blocking antibody (B6H12 and Ab400), IgG and no antibody conditions (data not shown)." (PMID 26093091, 2015). "We could observe strongly up-regulation of CD47 in 17 out of 20 osteosarcoma patients compared to those without invasive features (n = 10) (p < 0.001, Fisher's test)." (PMID 26093091, 2015). "However, in osteosarcoma cells, HIF-1α and HIF-2α expression levels were not obviously increased upon doxorubicin treatment, suggesting that HIF-mediated signaling is not evident in inducing CD47 upregulation in osteosarcoma and mechanisms that regulate CD47 expression can be tumor type-dependent." (PMID 36274066, 2022). "However, CD47 gene expression was not significantly different between the cell lines (inhibited or not inhibited by M2-like macrophages), as concluded from previously published genome-wide gene profiling data of osteosarcoma cell lines (data not shown)." (PMID 24612598, 2014).
non-small cell lung carcinoma (37 papers, 2014 to 2026). A group of at least three distinct histological types of lung cancer, including non-small cell squamous cell carcinoma, adenocarcinoma, and large cell carcinoma. "This study aims to investigate the effects of long noncoding RNA (lncRNA) on the phagocytosis of macrophage via CD47 and the proliferation of non-small cell lung cancer (NSCLC) via TIPRL." (PMID 38383737, 2024). "For example, NFκB TF has been shown to activate CD47 expression by binding to the distal enhancer elements in cells derived from breast, cervical, and non-small lung cell carcinomas." (PMID 39742254, 2024). "As discovered by Yang and others, coexpression of PD-L1 and CD47 predicts survival and illuminates future dual-targeting immunotherapy in non-small cell lung cancer." (PMID 35966889, 2022). "The downregulation of CD47 inhibits tumor growth, cell invasion, and metastasis in non-small-cell lung cancer." (PMID 36611344, 2022). "For both A549 and MDA-MB-231, elevated CD47 levels have been reported and are considered to be a driver for metastasis for the respective tumor type (non-small cell lung cancer [NSCLC], A549 cells; triple-negative breast cancer, MDA-MB-231 cells)." (PMID 34729396, 2021). "One recent study on non-small cell lung cancer suggested that CD47 blockade could enhance macrophage infiltration." (PMID 33765961, 2021). "However, the role of CD47 in the tumor microenvironment of non-small cell lung cancer has still not been exhaustively described, especially the role of CD47 in tumor-associated macrophages in non-small cell lung cancer has not been studied." (PMID 39652550, 2024). "However, it is largely unknown whether CD47 overexpression drives metastasis and how CD47 lead to tumor metastasis in non-small cell lung cancer (NSCLC)." (PMID 27411490, 2016). "Accordingly, CD47-PD-L1-bispecific antibody PF-07257876 has entered a Phase I clinical trial for patients suffering from HNSCC, non-small cell lung cancer (NSCLC), and other PD-L1-positive carcinomas refractory and naïve to ICI (NCT04881045)." (PMID 40121428, 2025). "In non-small cell lung cancer (NSCLC), approximately two-thirds of tumor samples exhibit CD47 overexpression, correlating with increased SIRPα on TAMs." (PMID 40079009, 2025). "In non-small cell lung cancer (NSCLC) patients, high CD47 expression has been closely related with poor prognosis." (PMID 40421217, 2025). "Another study conducted in non-small cell lung cancer (NSCLC) tumor tissues and cell lines demonstrated that CD47 is overexpressed in these tumors and is significantly associated with clinical staging, lymph node metastases, and distant metastases." (PMID 38493445, 2024). "AETC reduced CD47 levels in non-small cell lung cancer (NSCLC) cells and Lewis tumor xenograft mice, enhancing immunity to NSCLC by triggering ubiquitination and degradation of CD47." (PMID 38474640, 2024). "Previous studies have identified CD204+ TAMs as prognostic markers in non-small cell lung carcinoma (NSCLC), especially in lung adenocarcinoma, and the combined use of CD47 and CD68 was reported to predict the survival of eastern-Asian patients with NSCLC." (PMID 36077342, 2022). "High CD47 expression has been demonstrated to correlate with a poor outcome in AML, chronic myelogenous leukemia, NHL and some solid tumors (e.g., breast cancer, renal cell carcinoma, non-small cell lung cancer, thyroid cancer, etc.)." (PMID 36726125, 2023). "In non-small cell lung cancer, CD47 overexpression was not a prognostic factor." (PMID 33765961, 2021).